GNG13 (G protein subunit gamma 13)
Description:
Guanine nucleotide-binding proteins (G proteins) are involved as a modulator or transducer in various transmembrane signaling systems. The beta and gamma chains are required for the GTPase activity, for replacement of GDP by GTP, and for G protein-effector interaction.
Synonyms: h2-35; G(gamma)13; HG3J
Tractability: Antibody: UniProt places it where antibodies can reach, with high confidence; its Gene Ontology location is reachable by antibodies, with high confidence.
Gene: Protein-coding gene on chromosome 16 (798,041 to 800,734, reverse strand). Ensembl gene ENSG00000127588.
Subcellular location: Cell membrane
Pathways (Reactome):
Signal Transduction: Ca2+ pathway; Extra-nuclear estrogen signaling; G alpha (12/13) signalling events; G alpha (i) signalling events; G alpha (q) signalling events; G alpha (s) signalling events; G alpha (z) signalling events; G beta:gamma signalling through BTK; G beta:gamma signalling through CDC42; G beta:gamma signalling through PI3Kgamma; G beta:gamma signalling through PLC beta; G-protein activation; GPER1 signaling; Glucagon-type ligand receptors
Hemostasis: ADP signalling through P2Y purinoceptor 1; ADP signalling through P2Y purinoceptor 12; Prostacyclin signalling through prostacyclin receptor; Thrombin signalling through proteinase activated receptors (PARs); Thromboxane signalling through TP receptor
Metabolism: Adrenaline,noradrenaline inhibits insulin secretion; Glucagon signaling in metabolic regulation; Glucagon-like Peptide-1 (GLP1) regulates insulin secretion
Neuronal System: Activation of G protein gated Potassium channels; Inhibition of voltage gated Ca2+ channels via Gbeta/gamma subunits; Presynaptic function of Kainate receptors
Metabolism of proteins: Cooperation of PDCL (PhLP1) and TRiC/CCT in G-protein beta folding; Synthesis, secretion, and inactivation of Glucagon-like Peptide-1 (GLP-1)
Sensory Perception: Olfactory Signaling Pathway; Sensory perception of sweet, bitter, and umami (glutamate) taste
Cellular responses to stimuli: High laminar flow shear stress activates signaling by PIEZO1 and PECAM1:CDH5:KDR in endothelial cells
Disease: ADORA2B mediated anti-inflammatory cytokines production
Transport of small molecules: Vasopressin regulates renal water homeostasis via Aquaporins
Gene Ontology:
Molecular function: G-protein beta-subunit binding; protein binding
Biological process: G protein-coupled receptor signaling pathway; phospholipase C-activating G protein-coupled receptor signaling pathway; sensory perception of taste
Cellular component: heterotrimeric G-protein complex; plasma membrane; dendrite; synapse
Genetic constraint (gnomAD): Loss-of-function variants: 6 observed, 5.85 expected, observed/expected ratio (o/e) 1.03, 90% interval 0.55 to 1.8. That is too few expected variants to judge how well the gene tolerates losing a copy. Missense variants: 83 observed, 74.61 expected, observed/expected ratio (o/e) 1.11, 90% interval 0.93 to 1.34. Synonymous variants: 40 observed, 29.14 expected, observed/expected ratio (o/e) 1.37, 90% interval 1.07 to 1.77.
Homologues: Orthologues: chimpanzee GNG13 (100% identical), macaque GNG13 (100% identical), dog GNG13 (96% identical), guinea pig GNG13 (96% identical), mouse Gng13 (96% identical), rat Gng13 (96% identical), pig GNG13 (93% identical), tropical clawed frog gng13 (82% identical), zebrafish gng13b (75% identical), Caenorhabditis elegans gpc-2 (36% identical).
Diseases named in the same sentence as GNG13 in open-access papers:
GNG13 is named in the same sentence as 14 diseases in open-access papers, as found by Europe PMC text mining. Sharing a sentence is not in itself a finding about the gene and the disease. The quoted sentences say what the papers report.
breast carcinoma (3 papers, 2019 to 2021). "The dysregulation of GNG13 was implicated in the pathology of breast cancer and an association between high GNG13 expression and a malignant phenotype of gastrointestinal stromal tumor has been reported." (PMID 34600545, 2021). "In previous studies, the dysregulation of GNG13 was only found to be involved in the disease program of breast cancer." (PMID 31791268, 2019). "Of them, CXCL10, CXCL9, CCL11, CCR8, and GNG13 up-regulate breast cancer, while the other genes download-regulate breast cancer." (PMID 31874629, 2019).
Alzheimer disease (1 paper, 2022). A progressive, neurodegenerative disease characterized by loss of function and death of nerve cells in several areas of the brain leading to loss of cognitive function such as memory and language. "For instance, Gng13 may regulate the lymphangiogenesis, and it may be a potential marker of Alzheimer's disease." (PMID 36185082, 2022).
fibrosis (1 paper, 2024). the formation of excess fibrous connective tissue in an organ or tissue in a reparative or reactive process. "At 25 dpi, the percentages of fibrosis areas in WT (12.3%) and Gng13-cKO (26.3%) were significantly more than their corresponding ones at 0 dpi." (PMID 38836551, 2024).
keloid (1 paper, 2021). An irregularly shaped, elevated mark on the skin caused by deposits of excessive amounts of collagen during wound healing. "The identification of GNG13 and HTR1A as hub genes is consistent with keloids sharing some characteristics with cancer." (PMID 34600545, 2021). "The mRNA levels of NPY, ADCY8, GNG13 and HTR1A were significantly augmented in keloid compared with normal skin samples ***p < 0.001." (PMID 34600545, 2021). "GNG13, ADCY8, NPY and HTR1A may act as core genes in keloid formation and these core genes establish relationship with SP1 and miRNA (hsa-mir-372, hsa-mir-20, hsa-mir-10b), which may influence multiple signaling pathways in the pathogenesis of keloid." (PMID 34600545, 2021).
prostate carcinoma (1 paper, 2021). A carcinoma that arises from epithelial cells of the prostate gland. "GNG13 also was identified as a hub gene in PTEN-mutated prostate cancer." (PMID 34600545, 2021).
cancer (2 papers, 2021 to 2024). A tumor composed of atypical neoplastic, often pleomorphic cells that invade other tissues. "The other carcinogenesisrelated gene, GNG13, is a transduction factor for the G protein-coupled seven transmembrane helix receptors, which are associated with cancer development." (PMID 34600545, 2021).
infection (2 papers, 2023 to 2024). The state of being infected such as from the introduction of a foreign agent such as serum, vaccine, antigenic substance or organism. "(A) Gng13-cKO mice showed greater bodyweight loss than WT or Trpm5-/- mice over days post-infection." (PMID 38836551, 2024). "The uninfected Gng13-cKO and Trpm5-KO mice displayed significantly more activated caspase 3, 8 or 9-positive cells than uninfected WT mice whereas the infection did not significantly alter the number of activated caspases 3, 8 or 9-positive cells in either the Gng13-cKO or Trpm5-KO proximal colon." (PMID 37954611, 2023).
GNG13 also shares sentences with these, for which no sentence is quoted: Cerebral ischemia (1 paper); congenital stationary night blindness (1); gastrointestinal stromal tumor (1); mastitis (1); polyp (1); retinoblastoma (1); tumor (1).